CDK4 (cyclin dependent kinase 4)
Diseases named in the same sentence as CDK4 in open-access papers (continued):
Sharing a sentence is not in itself a finding about the gene and the disease.
pancreatic cancer (continued). "As a high proportion of pancreatic tumours carry aberrations in G1/S checkpoint machinery, targeting PDAC subtypes that are dependent on CDK4/6 signalling may therefore be a reasonable therapeutic approach." (PMID 30428574, 2018). "P276-00, a CDK1, CDK4, and CDK9 inhibitor, could sensitise pancreatic cancer cells to gemcitabine-induced apoptosis." (PMID 30340359, 2018). "Surprisingly, we found that four crucial microRNAs (miR-34a-5p, miR-195-5p, miR-30c-5p, and miR-130b-3p) regulated the expression of many mRNAs (Cdk4, Cdk6, VEGF, IKKα, MEK1, E2F3, Rac1, E2F1, ERK1, and CDC42) and their proteins, and thus were crucial to the anti-pancreatic cancer effects of DHA." (PMID 27613829, 2016). "To search for therapeutic targets in pancreatic cancer with SEMA6C downregulation, we applied L1000CDS2 analysis and found that cell cycle-related inhibitors, including those against topoisomerase or CDK4/6, may be potential drugs for the treatment of SEMA6C-low pancreatic tumors." (PMID 35269749, 2022). "The fact that treatment alone with CDK4/6 inhibitors seems not very promising for pancreatic cancer, the CDK4/6 inhibition-mediated metabolic state might be additionally targeted." (PMID 30340359, 2018). "To determine protein levels of the mRNAs modulated by DHA via microRNAs, we next examined Cdk4, Cdk6, VEGF, IKKα, MEK1, E2F3, Rac1, E2F1, and CDC42 protein levels, which affect growth, inhibit angiogenesis, and promote apoptosis in DHA-treated and vehicle-treated pancreatic cancer cells." (PMID 27613829, 2016). "Furthermore, we demonstrated that miR-196a promoted pancreatic cancer proliferation through G0/G1 arrest and decreased Cyclin D1 expression and CDK4/6 expression but not apoptosis." (PMID 24504166, 2014). "Importantly, in pancreatic cancer, the anti-tumorigenic activity of IL-33 has been demonstrated through tumor cell-intrinsic downregulation of cellular proliferating proteins, such as CDK2 and CDK4, and upregulation of pro-apoptotic molecules, such as Bax and TRAIL." (PMID 34209038, 2021).
colon carcinoma (80 papers, 2010 to 2026). "Furthermore, we show the efficacy of the Cdk4/6 inhibitor in vivo for inflammation-associated colonic tumors." (PMID 37845228, 2023). "Previous studies have shown that the lncRNA STEAP3-AS1 affects the expression of CDKN1C, CDK2, and CDK4 and histone H3 acetylation, which are involved in regulating cell cycle progression in colon cancer." (PMID 40665344, 2025). "It has been reported that BA treatment in the colon cancer cell line HCT-116 caused a decrease in cyclin-dependent kinases such as cyclin D, cyclin E, CDK2 and CDK4." (PMID 40142291, 2025). "Zhang and Cui found that METTL1 promotes the proliferation of colon cancer cells through stabilizing CDK4 via m7G modification." (PMID 38967523, 2024). "This interaction stimulates SMAD3 phosphorylation and activates the SMAD2-3-4 signaling pathway, resulting in the inhibition of cyclin D1/CDK4 expression and leading to G1 cell cycle arrest in colon cancer cells." (PMID 38338430, 2024). "Further, the mutational inactivation of TGFβRII has been discussed to increase G1/S transition kinase activity of CDK4 leading to colon cancer cell proliferation." (PMID 38256034, 2024). "In a colon cancer study, simvastatin was shown to mediate tumor-cell apoptosis by downregulating CDK4, which is a key protein in cell-cycle regulation." (PMID 39360264, 2024). "In conclusion, our study demonstrated that AGA extract has potential to inhibit the proliferation, metastasis by inducing apoptosis and G1 phase arrest efficiency by inhibiting the CDK2, CDK6/CDK4 proteins in colon cancer cells." (PMID 36597025, 2023). "Several studies have revealed that in addition to blocking the tumor cell cycle, CDK4/6 inhibitors can upregulate MHC-I expression in colon cancer cells." (PMID 35562811, 2022). "In terms of cell-cycle regulation, it was previously found that EGC kept Lovo colon cancer cells in the G1 phase and inhibited the expression of cyclin D1 and CDK4 in tumor cells." (PMID 36500365, 2022). "For example, coroglaucigenin, a Calotropis gigantean-derived compound, shows antiproliferation, autophagy, and senescence in colon cancer cells by dissociating HSP90 with CDK4 and AKT, degrading CDK4, and inactivating AKT." (PMID 36139919, 2022). "A growth-promoting effect of aTGFβ1 has been described previously in MDA-MB-231 cells and in colon carcinoma cells with aTGFβ regulating the cell cycle through a pathway different from exogenous TGFβ with respect to sensitivity of p21WAF1 and CDK4." (PMID 33802809, 2021). "After GSPT1 was silenced in HCT116 colon cancer cells, the expression of CyclinD1, CDK4/6, cyclinE, CDK2, p21, and p27 was detected by Western blot." (PMID 33819920, 2021). "The molecular mechanism studies suggest that CDK2/cyclin E and CDK4/cyclin D are involved in the inhibition of colon cancer cell proliferation by fargesin via p21WAF1/Cip1 and c-Myc, respectively." (PMID 33669811, 2021). "It has been reported that c-Myc induced cell proliferation is generally associate with an increase in CDK4 and CDK6 activities, which regulated G1 progression in colon cancer cells." (PMID 34659577, 2021). "The results show that TDZs can induce the degradation of cyclin D1 and CDK4, and the expression of p21 and p27, which is consistent with their inhibition of G1 to S-phase progression in colon cancer cells." (PMID 32170185, 2020). "The analysis of the expression of cell cycle regulators revealed that 8-hydroxyquinaldic acid inhibited the expression of cyclin D1 and CDK4 in both colon cancer cell lines." (PMID 32260268, 2020). "Collectively, NSC 95397 treatment promotes p21 expression, reduces CDK4/6 expression and Rb phosphorylation, and thus suppresses the proliferation of colon cancer cells." (PMID 29857489, 2018). "In pathological condition, RUNX1T1 is shown to promote microglial proliferation by regulating CDK4, but represses the proliferation and increases 5-flurouracil (5-FU) sensitivity in a colon cancer cell line (HCT116)." (PMID 28640846, 2017).
colon carcinoma (continued). "In the present study, we found that DDA1 promoted colon cancer cell proliferation and positively modulated cell cycle proteins including Ki-67, CyclinD1 and CDK4/6 in vitro and in vivo, which resulted in cell cycle S-phase arrest." (PMID 26942699, 2016). "For example, poor prognosis was reported to be associated with low DLC1, low CDKN2A/B and high CDK4 in lung cancer, and low DLC1, low CDKN2B, and high CDK6 in colon cancer." (PMID 25425654, 2014). "In detail, research has revealed that ginsenoside Rg3 disrupts the cell cycle at G0/G1 phase via the EGFR/Ras/Raf/MEK/ERK pathway in lung cancer (A549), liver cancer (Hep G2) cells, and the formation of Cyclin D1, CDK2, and CDK4 in colon cancer (SW620 and LoVo) cells." (PMID 40490812, 2025). "Combined with these findings, we speculated that MMP1 might accelerate the cell cycle transition of colon cancer cells by regulating cdc25a/CDK4-cyclin D1 and p21/cdc2-cyclin B1 complexes through alteration in the expression of c-Myc and ETV4." (PMID 34753916, 2021). "Furthermore, we also proved the positive relationships between the expression levels of CASC21 and co‐expressed cell cycle‐related genes including CCND1 and CDK4 by RNA sequencing using 20 colon cancer tissues." (PMID 31965704, 2020). "However, their influence on the tumor immune microenvironment is also of concern, and preclinical studies have shown that CDK4/6 inhibition can increase antitumor immunity in lung and colon cancer 11,12." (PMID 32929370, 2020). "miR-218 has been reported to inhibit CDK4 expression in colon cancer." (PMID 25816091, 2015). "One such option that may be discussed based on our current observations in ACPA-negative RA patients is to test the selective cyclin-dependent kinase 4/6 (CDK4/6) inhibitor (Momilactone B) which is currently being investigated for treatment of colon cancer." (PMID 25138370, 2014). "In addition, we tested the effect of the dietary compound silibinin on the Cdk4 pathway in Apc−/+ mice and HT-29 colon cancer cells in culture." (PMID 23530816, 2013). "Pre-clinically, this combination is particularly efficacious against CT26 colon carcinoma cells, which interestingly harbor a Cdkn2a deletion and expresses functional RB, likely rendering it highly sensitive to the tumor-intrinsic immunomodulatory effects of CDK4/6 inhibition." (PMID 34025662, 2021). "Therefore, we conclude that Tet and the CCND1/CDK4 compound could form hydrogen bonds and a stable compound structure, which can inhibit colon cancer cells proliferation by regulating CCND1/CDK4 compound and its downstream proteins phosphorylated Rb (p-Rb)." (PMID 31040202, 2019). "Similarly, CDK4/6 inhibition has been shown to inhibit the proliferation of several colon cancer cell lines in vitro, induce regression of a human colon cancer xenograft (Colo-205), and induce regression of multiple myeloma xenografts which specifically overexpress CDK6." (PMID 25162504, 2014). "HTLV-1 Tax acts on genes indirectly by binding several TFs, such as TCF3, ELK1, and MYC in colon cancer, as well as POLB, BUB3, and CDK4, according to the HTLV-1 infection signaling pathway." (PMID 39228892, 2024). "This study revealed that remimazolam promoted the cell-cycle progression and proliferation of HCT8 colon cancer cells by upregulating CDK1, PTTG1, CDC25C, CDK4, PLK1, PCNA, Ki67, RNASEH2B, FEN1, Cyclin D1,CD44 CDK2, CDKN3, CDC45, IQGAP3, and CDK6." (PMID 38725628, 2024). "The protein of p16 can inhibit cyclin-dependent kinase 4 (CDK4) and CDK6 and p16 plays vital role as a tumor suppressor in various human malignant cancers, including colon cancer." (PMID 36961395, 2023). "CD155 also affects the activation of AKT in colon cancer; in CT26 and Sw620 colon cancer cells, the knockdown of CD155 inhibits the expression of Cyclin D1 and CDK4, inducing the arrest of the cell cycle in G1, further suppressing the growth of tumor cells." (PMID 36358792, 2022).
colon carcinoma (continued). "In contrast, in the CT26 colon carcinoma model, CD3+ T cell numbers were relatively unchanged following CDK4/6 inhibition." (PMID 34025662, 2021). "After GSPT1 was silenced, the expression of GSK-3β, p21, and p27 increased, and the expression of CyclinD1, CDK4/6, cyclinE, and CDK2 decreased; these changes affected the progression of colon cancer cells from G1 phase to S phase and blocked the cell cycle." (PMID 33819920, 2021). "It has been reported that decursin, which is derived from Angelica gigas Nakai, can decrease cyclin D1 and CDK4 expression in 253J human bladder cancer cells and HCT116 human colon cancer cells." (PMID 32349276, 2020). "In this study, we demonstrated that siphonodictyal B inhibits several kinases such as CDK4/6, CDK7, and PIM2 in addition to PI3K in vitro and that siphonodictyal B exhibits more potent cytotoxic effects than liphagal against human colon cancer cell lines." (PMID 31364822, 2019). "In the present study, we demonstrated that MUM256 EA reduced the proliferation of colon cancer cells by arresting cells at G1 and G2 phases through the modulation of cell-cycle regulatory proteins including p21, cyclin B1, CDK2, CDK4 and cdc25A phosphatase." (PMID 31698795, 2019). "Our results have shown that c-Myc can lead to reaccumulation of cyclinD1, CDK4 and CDK6 in hypoxia, and this potentially explain the G1/S switch induced by c-Myc in colon cancer cells in a low-oxygen environment." (PMID 27793037, 2016). "Studies of lung and colon cancer show that underexpression of DLC1 frequently co-occurs with deregulated expression of cell cycle genes such as CDK6, CDK4, CDKN2A, and CDKN2B." (PMID 25425654, 2014). "In this vein, the profiling of 13,942 colon cancers revealed a differential expression of immune-related genes and TME cell infiltration depending on the CDK4/6 expression, hence contributing to the identification of markers useful to assess the response to immune checkpoint inhibitors (ICIs)." (PMID 41388212, 2025). "Both CDK4 and pRb positively correlated with CDKL3 in the colon cancer tissues." (PMID 38963708, 2024). "Furthermore, 5-LO expression was up-regulated upon inhibition of central cell cycle–promoting factors such as CDK4/6 (palbociclib) and E2F1, whereas overexpression of b-Myb attenuated 5-LO levels in the colon cancer cells." (PMID 36849252, 2023). "Similarly, lncRNA HAGLR targeting the miR-185-5p/CDK4/CDK8 axis promoted proliferation, migration, and invasion of colon cancer in vitro and in vivo." (PMID 35571488, 2022). "Most notably, CDK4/6i increases expression of antigen presenting genes (H2d1, H2k1, B2m, Erap1, Tap1, Tap2) and surface expression of MHC I and MHC II in several mouse and human breast and colon carcinoma pre-clinical models." (PMID 34025662, 2021). "Taken together, these results suggest that GSPT1 regulates CyclinD1, CDK4, and Cdk6 through GSK-3 β, and indirectly affects the expression of cyclinE and CDK2 through p21 and p27, thus regulating the transformation of colon cancer cells from the G1 phase to S phase and promoting tumor progression." (PMID 33819920, 2021). "In another study, geldanamycin was found to inhibit cyclin E/CDK2 and CDK4 in human prostate (DU145) and human colorectal (HT29) cancer cell lines, and it showed synergistic activity with the CDK 4/6 inhibitor (palbociclib) in HCT116 colon cancer cells." (PMID 33050377, 2020).
colon carcinoma (continued). "Moreover, in cell lines derived from oral squamous cell carcinoma (HSC-2, HSC-3, and HSC-4) and colon carcinoma (DLD-1), α-mangostin induced G1 arrest by downregulating CDK4, CDK2, cyclin D3, and cyclin E, as well as through the upregulation of the p27kip1 and p21waf1/cip1 CDK inhibitors." (PMID 34885809, 2021). "To discover more effective and less toxic CDK inhibitors, we have used computer-aided strategy to discover two CDK2 inhibitors, Adapaline and Fluspirilene for liver cancer and colon cancer, a CDK4/6 inhibitor Rafoxanide for skin cancer but not very effective for HCC." (PMID 34335258, 2021). "Moreover, multiple reports indicated that CDK4 could promote cell invasion in human tumors, such as non-small-cell lung cancer, gastric cancer and colon cancer." (PMID 34719318, 2021). "Although LOC441461-knockdown-induced suppression of CCNB1 was observed in all colon cancer cells, the suppression of CCND1 and CDK4 was observed in SW620, DLD-1, and LS174T cells but not LoVo cells." (PMID 33126743, 2020).
hepatocellular carcinoma (80 papers, 2011 to 2026). A malignant tumor that arises from hepatocytes. "Cyclin D1, associated with CDK4, controls glucose metabolism in hepatic carcinoma cells." (PMID 32709889, 2020). "Kinase AMPK was suggested as a target of inhibition for palbociclib, independently of CDK4/6, in hepatocellular carcinoma cells, while the two other inhibitors, abemaciclib and ribociclib had no inhibitory effect in this kinase." (PMID 40699853, 2025). "A gene set enrichment analysis in hepatocellular carcinoma has revealed CDK4 expression to be reversibly correlated with cytotoxic lymphocyte infiltration." (PMID 40699853, 2025). "Research indicates that HCV core protein also downregulates p16 levels via ubiquitin-proteasome pathway degradation, releasing its inhibition on CDK4/6 and stimulating human hepatocellular carcinoma cell growth." (PMID 41488306, 2025). "Western blot analysis showed that with the increase in abemaciclib concentration, the expression of CDK4 in hepatoma cell lines decreased more significantly." (PMID 38231074, 2025). "A recent study reported that VPS9D1‐AS1 interacted with HuR to affect the stability and expression of the CDK4 mRNA, thus impacting hepatocellular carcinoma (HCC) cell proliferation." (PMID 39614424, 2024). "A previous study showed that miR-122 acts as a tumour suppressor by regulating oncogenes such as cyclin G1, AKT3, and CDK4 in hepatocellular carcinoma." (PMID 38820252, 2024). "HDAC2 promoted hepatocellular carcinoma cell proliferation by increasing the expression of cell cycle-related proteins, such as cyclin D1, cyclin-dependent kinase 4 (CDK4), and phospho-Rb." (PMID 36968022, 2023). "TSPAN31 serves as a natural antisense transcript to inhibit CDK4 protein expression in human cervical cancer and hepatocellular carcinoma by targeting the 3ʹ-untranslated region of the CDK4 mRNA, thus suppressing cell proliferation." (PMID 36941633, 2023). "Pharmacologic inhibition of Cdk4 along with the downstream pyrimidine synthesis enzyme dihydroorotate dehydrogenase synergistically inhibits proliferation and survival of hepatocellular carcinoma cells." (PMID 38152849, 2023). "A selective CDK4/6 inhibitor, palbociclib, has been shown in recent years to inhibit cell proliferation in human hepatoma cell lines by promoting reversible cell cycle arrest." (PMID 36347033, 2022). "Inhibition of CDK4/6 has been shown to arrest cell-cycle progression in human hepatoma cells and mice." (PMID 35399296, 2022). "Four cell cycle-related genes (CDK4, CHEK1, CCNB1, and CDKN2A) were used to establish a risk score to predict the overall survival (OS) of patients with hepatocellular carcinoma (LIHC) in TCGA training set using LASSO Cox regression analysis." (PMID 36403263, 2022). "SPOCK1 downregulation of hepatoma cell lines by siRNA inhibited cell proliferation, upregulated p21 and p27, and interfered with pAkt and CDK4 expression." (PMID 35186754, 2022). "JMJD6 also expedites the proliferation and controls the cell cycle of hepatocellular carcinoma cells by directly targeting CDK4 and modulating histone modifications on the CDK4 promoter." (PMID 35359945, 2022). "CCND1, CDK4, MAPK1, CDKN1A, and E2F2 genes are linked to the development of hepatocellular carcinoma." (PMID 33959508, 2021). "Abemaciclib, an FDA-approved selective inhibitor of CDK4/6, inhibited the cell proliferation and tumor growth of hepatocellular carcinoma cells in vitro and in vivo." (PMID 33686022, 2021). "Previous studies on hepatocellular carcinoma have been reported that CDK4 exhibits a significant role in cell cycle regulation as a key factor in the signaling pathway, and thus can greatly inhibit the proliferation of cancer cells." (PMID 34784846, 2021). "Fucoidan from U. pinnatifida (commercially available or laboratory prepared) targeted p21Cip1/Waf and E2F-1 in PC-3 cells and cyclin D1 and CDK4 in mouse hepatoma Hca-F cells." (PMID 32046368, 2020).